DDX18 (DEAD-box helicase 18)
Description:
ATP-dependent RNA helicase that plays a role in the regulation of R-loop homeostasis in both endogenous R-loop-prone regions and at sites of DNA damage. At endogenous loci such as actively transcribed genes, may act as a helicase to resolve the formation of R-loop during transcription and prevent the interference of R-loop with DNA-replication machinery. Also participates in the removal of DNA-lesion-associated R-loop. Plays an essential role for establishing pluripotency during embryogenesis and for pluripotency maintenance in embryonic stem cells. Mechanistically, prevents the polycomb repressive complex 2 (PRC2) from accessing rDNA loci and protects the active chromatin status in nucleolus (By similarity).
Synonyms: MrDb; Has1
Tractability: Small molecule: a structure with a bound ligand is known. PROTAC: ubiquitination databases record sites on it; its protein half-life has been measured.
Target class: Enzyme
Gene: Protein-coding gene on chromosome 2 (117,814,673 to 117,832,379, forward strand). Ensembl gene ENSG00000088205.
Subcellular location: Nucleus, nucleolus; Chromosome
Subcellular location (Human Protein Atlas): Mitotic chromosome; Nucleoli; Nucleoli rim
Gene Ontology:
Molecular function: protein binding; RNA binding; RNA helicase activity; ATP binding; ATP hydrolysis activity; nucleic acid binding
Biological process: maturation of LSU-rRNA from tricistronic rRNA transcript (SSU-rRNA, 5.8S rRNA, LSU-rRNA); cellular response to estradiol stimulus
Cellular component: chromosome; membrane; nucleolus
Genetic constraint (gnomAD): Loss-of-function variants: 23 observed, 65.71 expected, observed/expected ratio (o/e) 0.35, 90% interval 0.25 to 0.5. The upper end of that interval is the gene's LOEUF score, 0.5, which puts it in group 2 of 6, group 1 being the genes least tolerant of losing a copy. Missense variants: 725 observed, 781.29 expected, observed/expected ratio (o/e) 0.93, 90% interval 0.87 to 0.99. Synonymous variants: 263 observed, 277.28 expected, observed/expected ratio (o/e) 0.95, 90% interval 0.86 to 1.05.
Homologues: Orthologues: chimpanzee DDX18 (98% identical), macaque DDX18 (97% identical), pig DDX18 (90% identical), dog DDX18 (89% identical), rabbit DDX18 (89% identical), guinea pig DDX18 (87% identical), rat Ddx18 (86% identical), mouse Ddx18 (86% identical), tropical clawed frog dpp10 (72% identical), zebrafish ddx18 (71% identical), Drosophila melanogaster pit (60% identical), Caenorhabditis elegans B0511.6 (50% identical). Paralogues in human: DDX10 (36% identical), DDX31 (32% identical), DDX21 (24% identical), DDX54 (24% identical), DDX50 (24% identical), DDX27 (24% identical), DDX55 (24% identical), DDX46 (23% identical), DDX24 (23% identical), DDX47 (22% identical), DDX3X (22% identical), DDX3Y (21% identical), and 26 more.
Diseases named in the same sentence as DDX18 in open-access papers:
DDX18 is named in the same sentence as 21 diseases in open-access papers, as found by Europe PMC text mining. Sharing a sentence is not in itself a finding about the gene and the disease. The quoted sentences say what the papers report.
gastric cancer (2 papers, 2020 to 2024). A primary or metastatic malignant neoplasm involving the stomach. "While DDX18 has been implicated in pancreatic and gastric cancers, its function in lung cancer and its contribution to lung cancer cell biology were unclear." (PMID 38732173, 2024). "Association of DDX18 expression with clinicopathological characteristics in 585 patients with gastric cancer." (PMID 33489896, 2020). "In this study, we first found that DDX18 was associated with the malignancy of gastric cancer." (PMID 33489896, 2020). "Further analysis showed that DDX18 could be applied as an independent risk factor for the prognosis of gastric cancer." (PMID 33489896, 2020). "Further analysis of the clinical and pathological data identified the high expression of DDX18 in gastric cancer tissues." (PMID 33489896, 2020). "(i) DDX18 can be treated as a molecular marker to assess the prognosis of patients with gastric cancer." (PMID 33489896, 2020). "In our study, we first discussed the differential expression of DDX18 in gastric cancer tissues and adjacent tissues, identifying the specific high expression of DDX18 in the cancer samples." (PMID 33489896, 2020). "The results of univariate analysis showed that positive DDX18 protein expression was present in 65.0% (380/585) of gastric cancer cases." (PMID 33489896, 2020). "We also explored its molecular mechanism by means of molecular cytology technology and animal experiments to elucidate DDX18 and to determine its role in the occurrence and development of gastric cancer." (PMID 33489896, 2020). "Cell and animal experiments have confirmed that DDX18 promotes the proliferation of gastric cancer cells." (PMID 33489896, 2020). "To identify the role of DDX18 in the tumorigenic ability of gastric cancer cells in vivo, we also established a subcutaneous gastric cancer xenograft model." (PMID 33489896, 2020). "We evaluated the clinical significance and prognostic value of candidate gene DDX18, which is overexpressed in gastric cancer tissues." (PMID 33489896, 2020). "Subsequently, we analyzed the relationship between the DDX18 protein level and the clinicopathological features of gastric cancer in 585 cases of gastric cancer." (PMID 33489896, 2020). "Based on the clinical prognosis of patients, we confirmed that DDX18 is abnormally highly expressed in patients with advanced gastric cancer and is closely related to a poor prognosis." (PMID 33489896, 2020). "By combining this with TCGA data and our cohort, we finally filtered out DDX18, which was upregulated in gastric cancer tissues, for further investigation." (PMID 33489896, 2020). "Coimmunoprecipitation, small RNAseq, and western blotting were performed to explore the mechanism of action of DDX18 in gastric cancer." (PMID 33489896, 2020). "Conversely, in gastric cancer, DDX18 promotes tumorigenesis through a distinct pathway." (PMID 38732173, 2024). "Conversely, in gastric cancer, DDX18 fosters tumor development by impacting microRNA-21 maturation." (PMID 38732173, 2024). "Moreover, we provide a preliminary experimental basis and theoretical basis for the future study of DDX18 as a new target for the treatment of gastric cancer." (PMID 33489896, 2020). "Combined with the analysis of clinical prognosis data, we found that DDX18 was positively correlated with the degree of malignancy of gastric cancer and could significantly affect the prognosis of patients with gastric cancer." (PMID 33489896, 2020). "Next, we detected the expression of DDX18 in 585 cases of gastric cancer by IHC." (PMID 33489896, 2020). "Knockdown of DDX18 also substantially decreased gastric cancer cell migration and invasion." (PMID 33489896, 2020). "We performed cell function experiments to study the role of DDX18 in gastric cancer." (PMID 33489896, 2020). "Furthermore, we performed in vivo and in vitro experiments to detect the function of DDX18 in gastric cancer." (PMID 33489896, 2020).
gastric cancer (continued). "(i) DDX18 was upregulated in gastric cancer tumor tissues from a TCGA database and our cohort." (PMID 33489896, 2020). "Next, we examined DDX18 in 22 pairs of fresh gastric cancer tissues from a large sample set by quantitative PCR and western blot analyses, which confirmed that DDX18 was specifically highly expressed in gastric cancer tissues (P < 0.05)." (PMID 33489896, 2020). "In a previous study, we found that DDX18 is highly expressed in gastric cancer." (PMID 33489896, 2020). "In a previous study, we identified the role of DDX18 in gastric cancer cells and confirmed that DDX18 could promote the expression of microRNA-21." (PMID 33489896, 2020). "We detected the expression of DDX18 in gastric cancer cell lines." (PMID 33489896, 2020). "(ii) DDX18 could be a potential therapeutic target in gastric cancer." (PMID 33489896, 2020). "Therefore, we speculated that DDX18 may play an important role in the development and progression of gastric cancer." (PMID 33489896, 2020).
acute myeloid leukemia (1 paper, 2020). Acute myeloid leukemia (AML) is a group of neoplasms arising from precursor cells committed to the myeloid cell-line differentiation. "Dead-box RNA helicase 18 (DDX18) is an essential factor in cell cycle progression in zebrafish hematopoietic cells and is mutated in some patients with acute myeloid leukemia." (PMID 33133141, 2020).
glioma (1 paper, 2024). A benign or malignant brain and spinal cord tumor that arises from glial cells (astrocytes, oligodendrocytes, ependymal cells). "Currently, no data are available on therole played by the DDX18, ZNF12, andCRISPLD1 genes in patients with gliomas and low-grade gliomasin particular." (PMID 39539523, 2024).
head and neck squamous cell carcinoma (1 paper, 2025). A squamous cell carcinoma that arises from any of the following anatomic sites: lip and oral cavity, nasal cavity, paranasal sinuses, pharynx, larynx, and salivary glands. "It has also been shown to enhance the expression of DDX18 by removing DNA 6 mA modifications and regulating promoter activity, thereby promoting the proliferation of head and neck squamous cell carcinoma." (PMID 40867005, 2025).
leukemia (1 paper, 2024). A malignant (clonal) hematologic disorder, involving hematopoietic stem cells and characterized by the presence of primitive or atypical myeloid or lymphoid cells in the bone marrow and the blood. "Concurrently, the authors identified four non-synonymous sequence mutations of Ddx18 in human leukemia samples by using next-generation sequencing technology." (PMID 38993792, 2024). "Although the presence of the mutant allele (Ddx18-E76del) has been confirmed in human leukemia cases, a direct causal link between Ddx18 deletion or mutation and hematopoietic system regulation through ribosome assembly remains elusive." (PMID 38993792, 2024).
lung adenocarcinoma (1 paper, 2024). A carcinoma that arises from the lung and is characterized by the presence of malignant glandular epithelial cells. "To investigate the role of DDX18 in lung adenocarcinoma (LUAD) development, we employed a multifaceted approach." (PMID 38732173, 2024).
lung carcinoma (1 paper, 2024). "Our findings on the significant role of DDX18 in lung cancer progression warrant further investigation of its underlying molecular mechanisms." (PMID 38732173, 2024). "Mechanistically, we revealed that DDX18 promotes lung cancer cell cycle progression through transcriptional activation of CDK4." (PMID 38732173, 2024). "Collectively, these data strongly support the potential of DDX18 as a therapeutic target for lung cancer." (PMID 38732173, 2024). "Our findings regarding DDX18’s role in lung cancer progression enrich its multifaceted contributions in cancer biology." (PMID 38732173, 2024). "In the present study, we demonstrate that DDX18 expression is upregulated in lung cancer and correlates with poor prognosis." (PMID 38732173, 2024). "Our findings provide compelling evidence that DDX18 depletion induces G1 phase arrest in lung cancer cells, coinciding with a decrease in CDK4 protein expression." (PMID 38732173, 2024). "Collectively, our findings unveil a novel oncogenic role for DDX18 in lung cancer." (PMID 38732173, 2024). "Furthermore, DDX18 depletion significantly inhibits the proliferation, invasion, and migration of lung cancer cells in both in vitro and in vivo models." (PMID 38732173, 2024). "However, our findings suggest a disconnect between c-Myc expression and DDX18 levels in lung cancer, highlighting the possibility of cell type-specific regulatory mechanisms or the existence of alternative upstream regulators of DDX18." (PMID 38732173, 2024). "By targeting DDX18 and its ability to regulate CDK4 expression and influence cell cycle progression, we can potentially develop novel therapeutic strategies to impede lung cancer growth." (PMID 38732173, 2024).
lymph node metastasis (1 paper, 2020). "The depth of invasion (T stage), lymph node metastasis (N stage), and DDX18 expression were independent prognostic risk factors." (PMID 33489896, 2020).
melanoma (1 paper, 2024). A malignant, usually aggressive tumor composed of atypical, neoplastic melanocytes. "Among the 26 shared mutated genes in melanoma B16-F1GFP-D and B16-FGFP-M cells, two genes (Ddx18 and Tubgcp6) were amplified in both parental and dormant cells." (PMID 39223638, 2024).
pancreatic cancer (1 paper, 2024). "In pancreatic cancer, DDX18 promotes immune escape through STAT1 activation, shielding cancer cells from immune surveillance." (PMID 38732173, 2024).
prostate carcinoma (1 paper, 2017). A carcinoma that arises from epithelial cells of the prostate gland. "Fourteen DNA repair genes and 15 hormone-regulated genes contributed to the high trigger score for the 7p14.3 variant, of which DAZAP2, DDX18, SET, and XRCC5 were also significantly deregulated in SPOP mutant as compared to SPOP wild-type human prostate carcinoma cases." (PMID 28663546, 2017).
Stroke (1 paper, 2022). Sudden impairment of blood flow to a part of the brain due to occlusion or rupture of an artery to the brain. "DDX18 was identified to be associated with stroke, and serum PDCD11-AB levels may serve as a potential biomarker for TRANSIENT ischemic attack." (PMID 35571562, 2022).
tumor (6 papers, 2011 to 2025). "Mechanistically, DDX18 promotes tumor immune escape in PDA by transcriptionally activating STAT1 expression." (PMID 38732173, 2024). "Hematoxylin and eosin (H&E) staining revealed a looser cell organization in DDX18 knockdown tumor sections compared to controls." (PMID 38732173, 2024). "It is likely that DDX18 exerts its effects through distinct regulatory pathways depending on the cellular context and specific tumor type." (PMID 38732173, 2024). "After 5 days, DDX18 knockdown significantly decreased the proliferation rate of tumor cells by 63.0% (P < 0.001)." (PMID 33489896, 2020). "The expression of DDX18 was also closely related to tumor volume, Borrmann classification, degree of tumor differentiation, cancer embolus, lymph node metastasis, and TNM stage." (PMID 33489896, 2020). "HMGB2 promotes endocrine therapy resistance in tumor cells by regulating DDX18 expression." (PMID 41354099, 2025). "The expression level of DDX18 was closely related to tumor location, tumor size, Borrmann classification, differentiation, intravascular tumor thrombus formation, nerve invasion, depth of invasion, lymph node metastasis, and TNM staging but not to age or gender." (PMID 33489896, 2020). "Compared to control tumors, DDX18 knockdown significantly suppressed LUAD tumor growth, as evidenced by reduced tumor volume and weight." (PMID 38732173, 2024).
cancer (3 papers, 2020 to 2024). A tumor composed of atypical neoplastic, often pleomorphic cells that invade other tissues. "Further investigation into the precise mechanisms underlying DDX18’s context-specific functions in different cancers is warranted to elucidate its full oncogenic potential." (PMID 38732173, 2024). "While previous work showed DDX18’s involvement in tumorigenesis across various cancers, the mechanisms appear to be highly context-dependent." (PMID 38732173, 2024). "Emerging evidence suggests a multifaceted role for DDX18 in cancer progression." (PMID 38732173, 2024). "c-Myc, a well-established oncogene frequently dysregulated in cancer, has been reported to bind the DDX18 promoter, implying that it may potentially activate DDX18 transcription." (PMID 38732173, 2024).
infection (1 paper, 2025). The state of being infected such as from the introduction of a foreign agent such as serum, vaccine, antigenic substance or organism. "Using microscopy, we confirmed the prediction of our chaperone interaction analysis, observing colocalization of DDX10, DDX18, DDX50, and GTPBP4 with VICE domains upon infection with HSV-1." (PMID 40577456, 2025).
DDX18 also shares sentences with these, for which no sentence is quoted: Anxiety (1 paper); breast carcinoma (1); colon cancer (1); epilepsy (1); Parkinson’s (1); renal cell carcinoma (1).